RN7SL789P (RNA, 7SL, cytoplasmic 789, pseudogene)
Gene: Miscellaneous RNA gene on chromosome 19 (32,655,016 to 32,655,308, reverse strand). Ensembl gene ENSG00000242436.
Homologues: Orthologues: chimpanzee Metazoa_SRP (87% identical), macaque Metazoa_SRP (80% identical). Paralogues in human: RN7SL1 (77% identical), RN7SL2 (76% identical), RN7SL296P (75% identical), RN7SL3 (75% identical), RN7SL220P (74% identical), RN7SL5P (74% identical), RN7SL322P (74% identical), RN7SL732P (74% identical), RN7SL481P (74% identical), RN7SL7P (74% identical), RN7SL18P (73% identical), RN7SL333P (73% identical), and 701 more.